SF3B1 (splicing factor 3b subunit 1)
Diseases named in the same sentence as SF3B1 in open-access papers (continued):
Sharing a sentence is not in itself a finding about the gene and the disease.
endometrial cancer (9 papers, 2020 to 2025). Primary or metastatic malignant neoplasm involving the endometrium (mucous membrane that lines the endometrial cavity). "In our study, decreased cell viability and associated cell cycle regulators expression in SF3B1-depleted cells highlights its pro-proliferative role in endometrial cancer." (PMID 33040078, 2020). "Consistently, we found wide scale disruption of alternative splicing across the transcriptome, suggesting that SF3B1-driven alternative splicing has a pathogenic significance in endometrial cancer." (PMID 33040078, 2020). "Taken together, these data suggest that SF3B1 exerts its functions by generating mature splice variants and KSR2 is one such downstream effectors of SF3B1 function in endometrial cancers." (PMID 33040078, 2020). "Increased SF3B1 levels in tumors originated due to PTEN loss suggest that overexpression of SF3B1 coupled with PTEN loss might drive the endometrial cancer progression." (PMID 33040078, 2020). "Elevated levels of SF3B1 protein expression have been observed in human endometrial tumors as well as three different endometrial cancer cell lines." (PMID 38790189, 2024). "The in vitro experiments demonstrate that SF3B1 enhances endometrial cancer cell proliferation, cell cycle progression, migration, and invasion." (PMID 40729294, 2024). "Pharmacological inhibition of SF3B1 by pladienolide B reduces tumor growth in cervical cancer, hepatocellular cancer, glioblastoma, chronic lymphocytic leukemia, and endometrial cancer." (PMID 38012150, 2023). "Related studies on RNA-binding proteins have found that the splicing factor SF3B1 accelerates the growth of endometrial cancer cells by controlling KSR2 RNA maturation." (PMID 35715407, 2022). "Together, these results suggest that SF3B1 promotes migration and invasion behaviors of endometrial cancer cells." (PMID 33040078, 2020). "This enrichment analysis suggests that SF3B1 overexpression promotes pro-cancer-specific transcriptome in endometrial cancer." (PMID 33040078, 2020). "Further, we show that knockdown of SF3B1 or treatment with the SF3B1 inhibitor Pladienolide-B reduces cell viability, migration, and invasion of endometrial cancer cells in vitro and endometrial tumor cell growth in vivo." (PMID 33040078, 2020). "Using RNA-Seq approach, we identified ~2000 differentially expressed genes (DEGs) with SF3B1 knockdown in endometrial cancer cells." (PMID 33040078, 2020). "First, we found increased SF3B1 protein expression in human endometrial tumors and three endometrial cancer cell lines." (PMID 33040078, 2020). "Subsequently, bioinformatics analysis showed KSR2 as a potential candidate for SF3B1-mediated functions in endometrial cancer." (PMID 33040078, 2020). "Here, we report that SF3B1 protein is overexpressed in human endometrial tumor samples and endometrial cancer cell lines." (PMID 33040078, 2020). "In summary, we report that SF3B1 plays an important role in endometrial cancer initiation and progression possibly through regulating KSR2 mRNA maturation." (PMID 33040078, 2020). "Second, our in vitro data demonstrated that SF3B1 promotes endometrial cancer cell proliferation, cell cycle progression, migration, and invasion." (PMID 33040078, 2020). "As expected, we found SF3B1 regulated the KSR2 expression in endometrial cancer cells both at transcript and protein levels." (PMID 33040078, 2020). "Consistent with this, we found that tumors in a genetic mouse model of endometrial cancer (PRCre/+Ptenflox/flox) overexpress SF3B1 protein." (PMID 33040078, 2020). "Together, these results demonstrate that SF3B1 expression is elevated in endometrial cancer at protein level." (PMID 33040078, 2020). "Here, we present several pieces of evidence indicating that the splicing factor SF3B1 plays an important role in endometrial cancer pathogenesis." (PMID 33040078, 2020).
endometrial cancer (continued). "Furthermore, the suppression of SF3B1 has been shown to induce G2/M arrest in endometrial cancer cells and impede the maturation of KSR2 pre-mRNA5." (PMID 39910288, 2025). "SF3B1 promotes malignancy in pancreatic cancer, endometrial cancer, and glioblastoma." (PMID 38012150, 2023). "To investigate whether SF3B1 was involved in endometrial tumorigenesis, we first examined its expression in a tissue microarray containing 102 human endometrial cancer samples of various tumor grades." (PMID 33040078, 2020). "Furthermore, SF3B1 knockdown reduced in vitro proliferation, migration, and invasion of the endometrial cancer cell lines Ishikawa and AN3CA." (PMID 33040078, 2020). "Importantly, we found rescuing the KSR2 expression with SF3B1 knockdown partially restored the cell growth of endometrial cancer cells." (PMID 33040078, 2020). "Thus, uncovering the precise role of SF3B1 in the progression of endometrial cancer will increase our knowledge of spliceosome function in endometrial cancer." (PMID 33040078, 2020). "Additionally, we examined SF3B1 expression in one Type II endometrial cancer cell line, KLE (from a poorly differentiated tumor)." (PMID 33040078, 2020). "Importantly, whereas SF3B1-depleted RL-95-2 cells are in a growing phase still at 72 h, three other endometrial cancer cell lines with high SF3B1 levels were in diminished cell growth state." (PMID 33040078, 2020). "Given that SF3B1 expression was elevated in endometrial cancers, we wondered whether SF3B1 promotes endometrial cancer cell proliferation." (PMID 33040078, 2020). "Taken together, our data suggest that SF3B1 plays a crucial oncogenic role in the tumorigenesis of endometrial cancer and hence may support the development of SF3B1 inhibitors to treat this disease." (PMID 33040078, 2020). "Here, in an attempt to identify new prognostic and therapeutic targets, we focused on a new area for this cancer—alternative mRNA splicing—and investigated whether splicing factor, SF3B1, plays an important role in endometrial cancer pathogenesis." (PMID 33040078, 2020). "Therefore, future studies dovetailing transcriptomics and metabolomics may provide better understanding on the functional role of SF3B1 in endometrial cancer progression." (PMID 33040078, 2020). "However, more in-depth studies are required to test whether SF3B1 overexpression and PTEN loss are mutually exclusive in endometrial cancers." (PMID 33040078, 2020). "Together, these findings suggest that SF3B1 could be targeted to reduce endometrial cancer growth." (PMID 33040078, 2020). "Thus, SF3B1 protein expression may be a prognostic biomarker and a therapeutic target for treating endometrial cancer patients." (PMID 33040078, 2020). "The splicing factor SF3B1 promotes proliferation and invasion by regulating KSR2 RNA maturation in endometrial cancer cells." (PMID 39910288, 2025). "However, whether SF3B1 overexpression likewise promotes endometrial cancer progression is unknown." (PMID 33040078, 2020). "Moreover, consistent with minimal SF3B1 protein levels, RL-95-2 cells showed diminished impact of SF3B1 knockdown or PLAD-B treatment on cell viability and migration in comparison to other three endometrial cancer cells that have robust SF3B1 protein levels." (PMID 33040078, 2020). "Finally, we report that knockdown of SF3B1 alters mRNA maturation of the kinase suppressor of Ras gene KSR2 and KSR2 acts as a downstream mediator of SF3B1 function(s) in endometrial cancer." (PMID 33040078, 2020).
hepatocellular carcinoma (8 papers, 2014 to 2026). A malignant tumor that arises from hepatocytes. "Here, we identified the spliceosome component SF3B1 as a key regulator of cell fate in hepatocellular carcinoma (HCC), with its expression elevated in HCC tissues/cells versus adjacent non-tumor tissues." (PMID 42103729, 2026). "The high expression level of SF3B1 in hepatocellular carcinoma (HCC) has been correlated with increased tumor aggressiveness and shorter overall survival (OS)." (PMID 36505770, 2022).
glioma (6 papers, 2017 to 2025). A benign or malignant brain and spinal cord tumor that arises from glial cells (astrocytes, oligodendrocytes, ependymal cells). "SF3B1 somatic-mutations (SF3B1mut) previously associated to alter physiological protein function were characterized in 1953 glioma samples from 3 datasets (CGGA-dataset; TCGA-dataset; MSKCC-dataset)." (PMID 35086552, 2022). "Moreover, bioinformatic analyses revealed a potential diagnostic capacity of SF3B1 levels to discriminate between GBM/gliomas vs. control tissues from humans and mice, suggesting that GBM/glioma curse with a global dysregulation of SF3B1 in different species." (PMID 35086552, 2022). "Overall, few of the commonly associated glioma driver genes were mutated in the methylation cluster PA-like, and NF1 and SF3B1 were the only recurrently mutated genes in this cluster." (PMID 32555164, 2020). "Moreover, Sf3b1 expression was also significantly correlated with key glioma/spliceosome -markers (Mki67/Pdgfra/Rbm22/Sf3b1)." (PMID 35086552, 2022). "In the Glioma/NC group, 8 proteins (COL1A1, PRL, VWF, HBD, SF3B1, NME3, RRBP1, and CSRP1) were selected, with an AUC of 0.892 in the training set and 0.871 in the validation set (accuracy: 78.5%)." (PMID 39716938, 2025). "In fact, we demonstrate for the first time a drastic SF3B1 overexpression (at mRNA/protein levels) in different cohorts of GBMs vs. non-tumor tissues, which was also confirmed in EPed-glioma mouse models vs. control samples." (PMID 35086552, 2022).
mesothelioma (6 papers, 2021 to 2025). A usually malignant and aggressive neoplasm of the mesothelium which is often associated with exposure to asbestos. "A similar DSB repair defect was observed with ectopic expression of SF3B1K700E in SF3B1 wild-type cells and a mesothelioma-derived cell line harboring the SF3B1K700E mutation (H2595) compared with a matched SF3B1 wild-type control mesothelioma-derived line (H2591)." (PMID 35027467, 2022).
ovarian carcinoma (6 papers, 2018 to 2025). A malignant neoplasm originating from the surface ovarian epithelium. "Taken together, the results indicated that SF3B1 is associated with poor prognosis and low cytotoxic immune cell infiltration in ovarian cancer." (PMID 38012150, 2023). "Our results suggest that SF3B1 is highly expressed in ovarian cancer and is associated with poor prognosis and low cytotoxic immune cell infiltration." (PMID 38012150, 2023). "High levels of SF3B1 RNA expression were associated with poor PFS of ovarian cancer in the Kaplan–Meier Plotter database." (PMID 38012150, 2023). "A result shows that SF3B1 is shown to be overexpressed and related to low cytotoxic immune cell infiltration in ovarian cancer." (PMID 40721578, 2025). "Targeting SF3B1 reprograms the immunosuppressive tumor microenvironment in ovarian cancer and synergizes with ICB." (PMID 40721578, 2025). "The protein level of SF3B1 was higher in ovarian cancer tissues (n = 19) than in normal tissues (n = 84) based on the PNNL panel of the CPTAC cohort." (PMID 38012150, 2023). "In vitro experiments and mouse (C57/BL6) ovarian tumor (ID8) models were built to evaluate the synergistic effect of the combination of SF3B1 inhibitor and PD-L1 antibody in the treatment of ovarian cancer." (PMID 38012150, 2023). "Inhibition of SF3B1 induces pyroptosis in ovarian cancer cells and releases mitochondrial DNA (mtDNA), which is englobed by macrophages and subsequently activates them (polarization to M1)." (PMID 38012150, 2023). "The results show that SF3B1 is shown to be overexpressed and related to low cytotoxic immune cell infiltration in ovarian cancer." (PMID 38012150, 2023). "In summary, we concluded that BCL2L2 is a direct target gene of SF3B1 and that the inhibition of SF3B1 induces ovarian cancer cell pyroptosis at least partly through BCL2L2." (PMID 38012150, 2023). "Here, we explored the relationships among SF3B1, pyroptosis, and cytotoxic immune cell infiltration in ovarian cancer." (PMID 38012150, 2023). "As expected, the expression of SF3B1 was markedly increased in ovarian cancer, and high levels of SF3B1 were correlated with poor PFS and overall survival." (PMID 38012150, 2023). "Inhibition of SF3B1 induces ovarian cancer cell pyroptosis by splicing regulation of BCL2L2, resulting in the release of mtDNA." (PMID 38012150, 2023). "Taken together, the results suggested that inhibiton of SF3B1 induces pyroptosis of ovarian cancer cells." (PMID 38012150, 2023). "Inhibition of SF3B1 triggers pyroptosis in ovarian cancer cells and promotes infiltration of cytotoxic lymphocytes." (PMID 38012150, 2023). "We then conducted a RNAi screen of six splicing factors and found BUD31 and SF3B1 exhibited similar inhibitory effect on ovarian cancer cells." (PMID 36271053, 2022). "As a result, phosphorylated SF3B1 was upregulated in ovarian cancer cells with USP39 overexpression and was downregulated in those with USP39 depletion." (PMID 33731694, 2021). "SF3B1 had already been confirmed as a component of TA exosomes derived from various cancers such as colorectal and ovarian cancer." (PMID 29954402, 2018). "Based on this, we identified SF3B1, a splicing factor that is highly expressed in ovarian cancer and negatively correlated with prognosis and cytotoxic lymphocyte infiltration, through screening TCGA and CPTAC databases and validating with clinical tissue microarrays." (PMID 38012150, 2023). "Therefore, SF3B1 inhibitor holds significant potential in combination with ICB therapy of ovarian cancer." (PMID 38012150, 2023). "To confirm the significance of SF3B1 in the prognosis of ovarian cancer, we performed immunohistochemistry using a tissue microarray (TMA) containing 35 normal fallopian tube samples and 226 high-grade serous ovarian cancer samples from Qilu Hospital (Jinan, China)." (PMID 38012150, 2023).
ovarian carcinoma (continued). "Furthermore, combination of SF3B1 inhibitor and αPDL1 showed excellent efficacy in mice ovarian cancer models, indicating a good clinical application prospect in immunotherapy in ovarian cancers." (PMID 38012150, 2023). "Next, we characterized the functional consequences of inhibition SF3B1 in ovarian cancer." (PMID 38012150, 2023). "Moreover, pladienolide B increases cytotoxic immune cell infiltration in the ID8 mouse model as a SF3B1 inhibitor and increases the expression of PD-L1 which can enhance the antitumor effect of αPDL1 in ovarian cancer." (PMID 38012150, 2023). "To test whether USP39 modulate spliceosome activity via SF3B1, we measured phosphorylated SF3B1 in ovarian cancer cells with USP39 overexpression or knockdown." (PMID 33731694, 2021). "To further explore the effect of SF3B1 on immune cell infiltration of ovarian cancer, we injected the mouse ovarian cancer cells ID8 into C57BL/6 mice and administered pladienolide B, an SF3B1 inhibitor, or vehicle." (PMID 38012150, 2023). "Our study provided preclinical evidence for SF3B1 inhibition and ICB combination therapy in ovarian cancer." (PMID 38012150, 2023). "The data suggests that inhibition of SF3B1 improves the immune microenvironment of ovarian cancer and synergizes ICB immunotherapy, which provides preclinical evidence for the combination of SF3B1 inhibitor and ICB to ovarian cancer treatment." (PMID 38012150, 2023). "Studies have shown that SF3B1, SF3B2, and SF3B3 can regulate target gene expression by alternative splicing to promote cancer progression, also SF3B3 controls AS in renal cancer and SF3B4 in ovarian cancer by regulating AS of RAD52." (PMID 37091785, 2023). "Combining an SF3B1 inhibitor and ICB to treat ovarian cancer may be an ideal treatment." (PMID 40721578, 2025).
cardiac hypertrophy (5 papers, 2018 to 2024). "A more recent study demonstrates a novel molecular mechanism whereby hypoxia-induced upregulation of the splicing factor SF3B1 (Splicing factor 3B subunit 1) causes mis-splicing of ketohexokinase and triggers the onset of cardiac hypertrophy by enforcing fructolysis." (PMID 30051286, 2018). "Ketohexokinase, the central fructose-metabolizing enzyme in heart, is shown to be alternatively spliced during pathological cardiac hypertrophy by the splicing factor 3b subunit 1 (SF3B1)." (PMID 39045460, 2024). "HIF1α activation of SF3B1-dependent splicing of KHK enforces fructolysis to promote cardiac hypertrophy in response to pathologic stress." (PMID 29695975, 2018). "Myocardial hypoxia enhances fructose metabolism in human and mouse models of pathological cardiac hypertrophy through HIF-1α activation of SF3B and SF3B1-mediated splice switching of KHK-A to KHK-C." (PMID 32069878, 2020). "HIF1α could also activate SF3B1, a splicing factor mediating isoform switch of ketohexokinase from KHK-A to KHK-C in pathologic cardiac hypertrophy." (PMID 39045460, 2024). "It was demonstrated that splice factors as HIF-1α targets, which prompted the analysis of their RNA targets, unveiling mechanistic and functional linkages between HIF-1α, splice factor 3b subunit 1 (SF3B1), KHK-C splice isoform production and fructose metabolism in cardiac hypertrophy." (PMID 32069878, 2020). "Moreover, myocardial hypoxia activates fructose metabolism in human and murine models of cardiac hypertrophy through HIF-1α-driven activation of splice factor 3b subunit 1 (Sf3b1) and SF3B1-mediated splice switching of KHK-A to KHK-C." (PMID 32733884, 2020).
chronic myeloid leukaemia (5 papers, 2018 to 2023). "Previous evidences illustrate that RPL32 plays an important role in the SF3B1 mutation for chronic myeloid leukemia (CML) disease progression, CD52 helps identify molecular signature of CML and NFKBIA plays a strategic role in CML molecular response." (PMID 38096269, 2023). "The individual with the DNMT3A p.R693H variant had not had any haematological malignancy prior to death (at age 89 years), while the individual with the SF3B1 p.K666N variant had chronic myeloid leukaemia." (PMID 29641532, 2018).
colorectal cancer (5 papers, 2018 to 2025). A primary or metastatic malignant neoplasm that affects the colon or rectum. "Mutations in SF3B1 cause resistance to PB in WiDr and DLD1 colorectal cancer cell lines, indicating that SF3B1 is the primary target of PB." (PMID 33348896, 2020).
lung adenocarcinoma (5 papers, 2015 to 2022). A carcinoma that arises from the lung and is characterized by the presence of malignant glandular epithelial cells. "While the most of aberrant 3′-splice patterns were explained by SF3B1 mutations, we also detected nine SF3B1 wild-type tumors (including five lung adenocarcinomas)." (PMID 33057152, 2021). "Our study provides definitive evidence that genetic alterations of SUGP1 genocopy SF3B1 mutations in lung adenocarcinoma and other cancers." (PMID 33057152, 2021). "PTMs particularly phosphorylation of EGFR in lung adenocarcinoma, and SF3B1 in CLL has been reported/targeted." (PMID 35230971, 2022).
macrocytic anemia (5 papers, 2014 to 2024). Anemia that is characterized by increased red blood cell volume. "Loss-of-function mutations in zebrafish sf3b1 induce macrocytic anemias with enhanced TGF-β signaling, and inhibition of TGF-β signaling pathway can release the G0/G1 block of erythroid progenitors in the mutants." (PMID 34638816, 2021). "Also, mice or zebra fish carrying SF3B1 K700E mutations show macrocytic anemia suggesting this mutation is associated with increase cell size in certain cell types." (PMID 35478057, 2022). "Deficiency of sf3b1 in zebrafish embryos caused abnormal activation of the TGF-β signaling as well as cell cycle arrest and macrocytic anemia." (PMID 34638816, 2021).